STAT1 (signal transducer and activator of transcription 1)
Diseases named in the same sentence as STAT1 in open-access papers (continued):
Sharing a sentence is not in itself a finding about the gene and the disease.
infection (continued). "However, later in infection (24 h.p.i), the recognition of viral replication intermediates (ss/dsRNA) and/or structural DENV PAMPs may activate both NF-kB- and STAT1-dependent pathways, potentially playing a role in the induction of cytokine storm in DENV-2-infected MDMs." (PMID 40934228, 2025). "Interestingly, in our IP infections of Stat1 KO mice, we did not detect any VA1 RNA in the feces." (PMID 40304490, 2025). "Importantly, basal JAK2 and STAT1 transcript and protein levels were dampened by infection even in the absence of interferon, which could have implications for cytokine signaling beyond IFNγ." (PMID 39194253, 2024). "Therefore, the removal of STAT1 signaling on CD11c+ cells did not affect the protective host response in the early induction phase while it did have significant impacts on T cell responses after infection." (PMID 39324785, 2024). "Furthermore, infection of hepatitis C virus, influenza A virus, respiratory syncytial virus, human immunodeficiency virus, and herpes viruses, induce SOCS3 expression to antagonize STAT1/2 activation, implying SOCS3 can be a therapeutic target for the development of broad-spectrum antiviral drugs." (PMID 36930690, 2023). "Moreover, there was no translocation of STAT1 upon infection with WT or ΔORF6 SARS-CoV-2 at 24 hpi." (PMID 37377442, 2023). "Interestingly, while IRF9, STAT1, and STAT2 were found in the nucleus of IFN-I treated PAM cells after 8 hpi, their localization was primarily cytoplasmic after 16 hpi, suggesting that both attenuated and virulent strains impair the nuclear translocation at late times of the infection." (PMID 34512601, 2021). "However, disease in STAT-1 mice is protracted and not highly representative of human infections." (PMID 32841215, 2020). "However, neither STAT1 nor NF-κB p65 showed any activation upto 4 h post infection, suggesting that these two transcription factors may not be responsible for maintaining initial PD-1 level during infection." (PMID 28690843, 2017). "Thus, since phagocytosis involves the recognition and binding of bacteria by receptors on the cell surface, Stat-1 activation could vary according to the type of bacteria involved in the infection: Gram-positive or Gram-negative." (PMID 27437406, 2016). "Indeed, in the absence of STAT1, Toxoplasma-infected mice succumb rapidly to infection." (PMID 23527309, 2013). "Whether or not GBM patients who display an elevation in IFN/STAT1-mediated gene activation have a heightened resistance to virus-mediated infection and oncolysis remains to be determined, but if this proves to be so, it could form a rational basis for prescreening GBM patients for this therapy." (PMID 22242177, 2012). "In THP1 cells, physalin F inhibited SeV-induced phosphorylation of IRF3, STAT1, and STAT2 at 4 h post-infection, and had no marked effects on it at 8 h post-infection." (PMID 41599057, 2026). "It is known that in conventional infection, DENV-2 evades innate immune activation and IFN responses by a number of mechanisms, including its non-structural protein NS3’s inhibition of STAT1 and STAT2 signaling (36, –, 38)." (PMID 39902963, 2025). "Blockage of type I IFN signaling starting 2 h before infection with anti-IFNAR1 mAb prevented the upregulation of MLKL and STAT1, another ISG, seen in wild type macrophages, without affecting the basal level of MLKL and STAT1." (PMID 40950000, 2025). "P-STAT1, STAT1, and MX1 levels were similar across all siMETTL3 groups (Mock, VSV-ΔM51, VSV-Mwt, and VSV-Mwt-P1), with no further increase in P-STAT1, STAT1, or MX1 was observed after infection with any virus, compared to mock." (PMID 40214229, 2025). "Western blot analysis showed IBV infection did not promote the phosphorylation of STAT1 and STAT2 and significantly inhibited IFN-β-induced STAT1 phosphorylation at the late stage of infection (18 h.p.i.)." (PMID 39602452, 2024).
infection (continued). "MHV68 infection drives the increase in the ABC population; however, the role of STAT1 and IFNγ signaling in MHV68-driven ABC expansion has not been tested." (PMID 39440973, 2024). "At 24 h after infection, however, M1-GFP resulted in significant increases in the total STAT1 and p-STAT1 levels, while M1-NS3M did not." (PMID 37296165, 2023). "SARS-CoV-2 induced phosphorylation of STAT1, as well as rapid IFIT1 and OAS2 mRNA induction, suggest a similar host response to SARS-CoV-2 as that observed during mutant MERS-CoV-ΔNS4ab infection, and not that of WT MERS-CoV infection." (PMID 33811184, 2021). "Compared to lethal infection of Cd300lf+/-Stat1-/- littermates, intraperitoneal CR6 infection of mice lacking MNoV receptor CD300LF is significantly abrogated and is non-lethal." (PMID 33705489, 2021). "While we did not observe differences in IFNAR1, IRF3, STAT1, nor ISG15 expression induced by the two strains, IFNβ, LPG2, RIG1, and OAS1 were significantly induced after infection with Mb3601, but not H37Rv." (PMID 34307535, 2021). "When we checked phosphorylation levels of STAT1 and STAT3 at 6 h after infection in Vero cells, there was still no prominent effect of HCoV-OC43 infection." (PMID 34835005, 2021). "Previously we showed that EV-A71 infection did not alter the expression of IFNAR1 or JAK1, neither did it induce the degradation of STAT1 or STAT2." (PMID 34992585, 2021). "We found that phosphorylation of STAT1 and STAT2 in A549 cells pre-treated with IL-36γ was inhibited at each post-infection point in time, while no significant changes in Mx1, PKR, IAV-Ca07 NP, and M1 protein were observed." (PMID 33193319, 2020). "On the other hand, there was no distinct trend between infection with CVI988 and vvRB1B and the expression of cytokines and chemokines, such as IL-10, IFN-γ, STAT1, IRF1, CCL19, and CCL26." (PMID 32210095, 2020). "Immunoblot analysis indicated that steady-state levels of STAT1 and STAT2 were not affected by infection, while phosphorylation of STAT1 at Tyr701 and STAT2 at Tyr690 (p-STAT1 or p-STAT2) was greatly reduced in TBEV infection compared with VSV-infected cells." (PMID 32196427, 2020). "In contrast to the early timepoints postinfection, during late stages of infection, LCMV RNA levels were increased in the absence of RAG1, independent of STAT1." (PMID 32310998, 2020). "Since STAT1, STAT2 and likely PDLIM2 protein levels vary among cell types and during infection, we cannot rule out that PDLIM2 does not direct interferon independent degradation of STAT1 in other situations." (PMID 31374104, 2019). "For both genotypes, the levels of phospho-STAT1 and phospho-STAT3 are not significantly different 48h after infection." (PMID 29518136, 2018). "CHIKV infection alone did not induce STAT1 phosphorylation, suggesting that the amounts of type I IFN secreted during infections are not sufficient (lane 3)." (PMID 30380742, 2018). "To probe for STAT1 or STAT3 roles in IL-6-mediated inhibition of infection, we tested the effect of IL-6 (5 ng/mL, 14 h) on the knockout cells with or without infection with EHDV-TAU (48 h, multiplicity of infection moi = 0.5)." (PMID 29441069, 2018). "Mice with targeted disruptions of signal transducer and activator of transcription factor 1 (STAT1), which have severely impaired type I and III interferon (IFN) responses, did not develop persistent viremia following infection." (PMID 27834208, 2016). "In contrast, after infection with the persistent strain MNV-S99, no phosphorylation of Stat1 was detectable." (PMID 27294868, 2016). "In the real-time PCR assay and RT2Profiler PCR Array, wt ZJ1 induced high levels of ISGs at early period of infection in both A549 and DF1 cells, suggesting STAT1 signal transduction were not wholly inhibited." (PMID 26859759, 2016). "STAT1 was not obviously degraded in NDV-infected A549 cells; however, it seems that STAT1 proteins were sequestrated in the cytoplasm in the course of infection." (PMID 26859759, 2016).
infection (continued). "In co-IP assays performed at 8 h after infection, PML was found to interact with STAT1, STAT2, HDAC1, and HDAC2 in UV-HCMV-infected cells but not in uninfected cells." (PMID 25812002, 2015). "Twenty four host proteins (17 in the cytosol and seven in the nucleus) are up-regulated ≥1.5-fold by T3D infection but not by T1L infection, and four of these proteins (Mx1, ISG15, IFIT1, and STAT1) are up-regulated >3.5-fold by T3D." (PMID 25905045, 2015). "Therefore, although we propose that enhanced viral clearance in SOCS1−/−IFN-γ−/− mice is not due to increased IFN/STAT1 activation at the acute phase of infection, these SOCS1-regulated pathways may contribute to the resolution of inflammation after viral clearance." (PMID 25500584, 2014). "Subclinical infection of murine norovirus (MNV) was detected in a mixed breeding group of WT and Stat1−/− mice with no outward evidence of morbidity or mortality." (PMID 24225497, 2014). "Some of these molecules (IRF7, IRF9, STAT1, STAT2) are known ISGs and were upregulated in wild-type but not in IFNAR1−/−IL-28Rα−/− epithelia at 24 hours post infection." (PMID 24278020, 2013). "Infection with either pathogen does not affect native Stat-1 expression, however EHEC prevented Stat-1 tyrosine phosphorylation in response to IFNγ stimulation." (PMID 22253910, 2012). "Most recently, it was shown that infection of cells with type II Pru or NTE parasites does not inhibit IFNγ-induced STAT1 trafficking into the nucleus." (PMID 23240025, 2012). "Our preliminary analysis would confirm that infection of STAT1-/- mice with virulent WT MNV-1, can result in the induction of ISGs, even in the absence of STAT1, as we observed increased levels of CXCL10 and ISG54 at 3 days post infection." (PMID 22174679, 2011). "Therefore we would propose that during our studies in the STAT1-/- mouse model, it is likely that infection with the virus lacking VF1 leads to the induction of a subset of ISGs during virus replication at the primary site of infection, either directly via an unknown mechanism, or via STAT2." (PMID 22174679, 2011). "Infection with replicating, but not UV-inactivated virus, reduced IFN-β-induced STAT1 phosphorylation." (PMID 21949722, 2011). "The STAT-1 pathway, which is downstream of IFN induction, was not activated by infection with any virus containing B19R (wtNYVAC, NYVAC-C or NYVAC-C-KC)." (PMID 22096477, 2011). "The present data show that IFN-γ induces phosphorylation of STAT-1; its effects on membranous ICAM-1 levels are inhibited in a dose-dependent fashion by AG490 in the absence of infection." (PMID 18534017, 2008). "Knockdown of TLR4 or SLAMF1 did not substantially alter HMPV-induced STAT1 phosphorylation at early time points, although SLAMF1 depletion significantly reduced STAT1 phosphorylation at 20 h post-infection, consistent with the reduced HMPV-N mRNA and protein levels in these MDMs." (PMID 41346628, 2025). "Moreover, an augmentation in STAT1 phosphorylation was detected, induced by PolyI:C in a PKR/IFN-I-dependent manner, in the absence of infection." (PMID 40521699, 2025). "Although there is a significant increase in transcript levels of the known JAK-STAT negative regulator SOCS3 during infection, which can lead to JAK2 protein degradation, this does not explain the decrease in levels of both JAK2 and STAT1 at the transcript level." (PMID 39194253, 2024). "Activation of various upstream TCR signaling pathways leading to the production of IFN-γ, as well as STAT1 and IL-12, in mice vaccinated with the L-PaF formulation, but not in PBS vaccinated mice, is an indication that Pa infection proceeds differently in the vaccinated mice." (PMID 36918600, 2023). "Thus, our Stat1T385M/+ mouse model recapitulates several features of abnormal CD4 T cell differentiation seen in STAT1 GOF patients, but in the absence of infection." (PMID 37275873, 2023).
infection (continued). "The other two genes, ISG15 and STAT1, exhibited no considerable (p > 0.05) expression in CT followed by infection, which might be due to the intrinsic nature of the availability of Mx in normal fish species but may not be the case for ISG15 and STAT1." (PMID 36611649, 2022). "Western blotting analysis showed that compared with the mock-infected cells, both phosphorylated and non-phosphorylated forms of STAT1 as well as the expression of ISG15, were upregulated markedly in PEDV-infected cells, especially in the late stage of infection (18-24 hpi)." (PMID 35958569, 2022). "Additionally, infection in MDA5 knockout mice is not lethal, in contrast to that in Stat1 knockout mice, further suggesting the presence of other receptors that contribute to the restriction of viral replication (reviewed by Karst)." (PMID 34698626, 2021). "Notably, IRF9 expression was not affected by infection with either virulent or attenuated ASFV strains, supporting the idea that the virus specifically induces STAT1 and STAT2 degradation to counteract IFN-I signaling." (PMID 34512601, 2021). "Interestingly, STAT1−/− mice developed PDL-1+ macrophages at 8 weeks post-infection, but no enhancement in PDL-1 MFI was found compared to STAT1−/− naïve mice." (PMID 34684235, 2021). "Likewise, phosphorylation of STAT1 and STAT2 in 16HBE cells pre-treated with IL-36γ was mildly inhibited at 12 h after IAV-Ca07 infection, while no significant changes in Mx1, PKR, IAV-Ca07 NP, and M1 protein were observed." (PMID 33193319, 2020). "Similarly, TFIIB depletion after infection with rTHOV-ΔML (mixed stimulus) led to a decreased IFIT3 expression, but not STAT1, p65 or p38." (PMID 29709033, 2018). "Given that the phosphorylation of STAT1 can be negatively regulated by suppressors of cytokine signaling (SOCSs) and protein tyrosine phosphatases (PTPs), we examined their expression in BMMs with and without MHV-68 infection." (PMID 30075008, 2018). "Infection with ZIKV PR-2015 in the absence of IFNβ treatment induced minimal STAT1 phosphorylation and low levels of STAT2 phosphorylation, despite notable up-regulation of STAT1 and STAT2 total proteins." (PMID 28152048, 2017). "Infection of macrophages by Gram-negative bacteria induces the production of IFN-β, which acts in autocrine or paracrine fashion and triggers subsequent STAT1 phosphorylation." (PMID 26284031, 2015). "Interestingly, our data showed up-regulation of both STAT1 and STAT3 in the Hep-dG infection group, but not in rHep-Flury-infected cells." (PMID 26217322, 2015). "For human CD141+ DCs, infection-induced up-regulation of IFN-β and STAT-1 gene expression was low compared to CD14+ DCs and CD1c+ DCs, which might also reflect the lack of infection of the cells at these time points." (PMID 25474532, 2014). "Additional IFN-β treatment failed to induce more STAT1 phosphorylation in cells infected with hMPV for 15 h, compared to mock-infected IFN-β-treated cells, indicating that hMPV infection inhibits type I IFN-induced STAT1 phosphorylation, similar to what has been reported for RSV." (PMID 21949722, 2011). "However, neither infection with IPNV (for 12, 24 and 48 h) nor ISAV (for 12, 24, 48, 72 and 96 h) increased STAT1 expression." (PMID 20353564, 2010). "Whilst infection of monocytes with EBV for 20 hours led to the phosphorylation of Jak1, STAT1 but not Tyk2 nor STAT2, increased phosphorylation of these proteins could not be observed upon restimulation of infected cells with IFNα." (PMID 20689596, 2010). "In order to prove that early STAT1 inhibition is sufficient to block the TI protective phenotype, and not just downstream markers, we repeated the inhibitor regime with control or trained mice receiving either Fedratinib or DMSO, with or without S.Tm infection after 2 weeks." (PMID 39819562, 2025).
infection (continued). "Currently, it is not known whether STAT1 signaling competency is required in the same immune cell subsets to control YFV-17D and USUV infections; however, this could be explored through generation and infection of immune cell-specific STAT1 KO mice." (PMID 40694555, 2025). "For example, STAT1 and tyrosine kinase 2 (TYK2) did not influence infection alongside other positive regulators of IFN signaling, which we attribute to the fact that some gRNAs in the library may have not efficiently directed Cas9 to cut at their respective target gene loci." (PMID 39316623, 2024). "Immunoblotting assay results showed that PeV-A3 failed to induce STAT1, STAT2, IRF3, and NFκB p65 activation in FBS medium-maintained GBM cells; in contrast, phosphorylation of STAT1, STAT2, IRF3, and total NFκB p65 were detected in hPL-medium-maintained GBM cells with PeV-A3 infection." (PMID 35891479, 2022). "However, as CD8+ T cells naturally downregulate STAT1 during infection, they may become resistant to STAT1 dependent IFN signaling, leading to lack of STAT1-dependent phenotypes in antiviral CD8+ T cells, at least in our assays." (PMID 35968944, 2022). "STAT1 mRNA levels were increased in both HRV16 and HRV1B infection than mock (p = 0.036 and p = 0.014, respectively) whereas STAT2 mRNA levels were increased in HRV1B infection, not in HRV16, than mock (p = 0.040), whereas IRF9 mRNA levels were not increased in HRV16 and HRV1B infection." (PMID 34838080, 2021). "No increase in STAT1 phosphorylation or PKR expression could be observed until 6 d following TULV infection of HMEC-1 or THP-1/PMA cells and no viral N protein was detectable in TULV-infected cells after the initial infection (0 h p.i.)." (PMID 31540120, 2019). "Further support for the prominent role of STAT1 activation in the restriction of EHDV-TAU infection in LNCaP-JAK1 cells and in EHDV-TAU induced oncolysis by non-productive infection comes from the observed effects of IFNγ, known to mediate antiviral effects through STAT1 homodimer formation." (PMID 29441069, 2018). "Studies with a specific PKR inhibitor revealed that the phosphorylation of STAT-1 serine 727 is only modestly dependent on PKR activity in cells expressing misfolding forms of an HLA-B27 molecule, unlike in control cells, at the early time points of infection, but the dependency increased over time." (PMID 23349666, 2013). "Quantification of the viral RNA genomes in infected tissues at days 3 and 5 post infection, as well as the gross differences in MNV-1 related pathology at day 5 are testament to the debilitated replicative ability of this virus in vivo even in the absence of STAT1." (PMID 22174679, 2011). "IFNAR−/−/IFNGR−/− (AG129) mice do not survive infection, yet STAT1−/−/IFNGR−/− mice remain healthy, demonstrating that STAT2 alone provides sufficient signaling via the type I IFN pathway for a functional antiviral response, despite the absence of both STAT1 and type II IFN signaling." (PMID 21379341, 2011). "In addition, in the JIMT-1 CD44−/CD24− non-CIC population expression of both STAT1 and STAT3 decreased 60 min after infection and no more P-STAT3 could be detected at this time point." (PMID 21079774, 2010). "There is abundant evidence that STAT-1 signalling is a key regulatory pathway; although not necessarily mediating all effects of IFN-γ, it made sense to first determine whether STAT-1 regulation is involved in mICAM-1 modulation during HRV-14 infection." (PMID 18534017, 2008). "Additionally, SOCS proteins that can downregulate JAK and STAT1 phosphorylation are actually induced by Toxoplasma infection, and the expression of the protein tyrosine phosphatases (PTPs) that are known to dephosphorylate JAK1, JAK2, or STAT1 are not downregulated by infection alone." (PMID 23240025, 2012).